SIN3B (SIN3 transcription regulator family member B)
Diseases named in the same sentence as SIN3B in open-access papers (continued):
Sharing a sentence is not in itself a finding about the gene and the disease.
tumor (continued). "Subsequently, we depleted CD8+ T cells in tumor‐bearing mouse, which led to rescue of tumor growth, highlighting the critical role of CD8+ T cells in mediating the anti‐tumoral effects of Sin3B deficiency." (PMID 39316363, 2024). "In consistent, analysis of PDAC patients who exhibited a favorable response to ICB therapy revealed lower expression levels of SIN3B in tumor tissues compared to non‐responders." (PMID 39316363, 2024). "Using murine PDAC models, we found that tumor cell‐intrinsic Sin3B loss reshapes the TME, increasing CD8+ T cell infiltration and cytotoxicity, thus impeding tumor progression and enhancing sensitivity to anti‐PD1 treatment." (PMID 39316363, 2024). "In murine PDCA models, tumor cell‐intrinsic Sin3B loss reshapes the TIME, characterized by a notable influx of immune cells into the tumor tissue, particularly an augmented presence and activity of tumor‐infiltrating CD8+ T cells." (PMID 39316363, 2024). "This suggests that SIN3B, as an epigenetic regulator, plays distinct roles in different tumors or even at different stages of the same type of tumor." (PMID 39316363, 2024). "Together, these results indicate that SIN3B levels are inversely correlated with anti‐tumor immune response and ICB therapy response in PDAC, suggesting its potential as a predictive biomarker for immunotherapy outcomes in PDAC patients." (PMID 39316363, 2024). "Among the collagens regulated by Sin3B loss, Col3a1 stood out as highly expressed in PDAC tumor cells, thus warranting for further validation." (PMID 39316363, 2024). "The findings suggest that targeting SIN3B can enhance cytotoxic T cell infiltration into the tumor site and improve immunotherapy efficacy in PDAC, offering potential avenues for therapeutic biomarker or target in this challenging disease." (PMID 39316363, 2024). "Finally, we performed IHC for SIN3B on our UW1 cohort and scored both the percent SIN3B+ tumor nuclei and the intensity of SIN3B staining." (PMID 40168074, 2025). "Reduced SIN3B levels impair cellular differentiation and cell cycle withdrawal in response to oncogenic stimuli, and SIN3B is reported to variably promote or suppress tumor invasion depending on cancer type." (PMID 40168074, 2025). "Our study is the first to unveil the regulatory role of SIN3B in the tumor immune microenvironment." (PMID 39316363, 2024). "Consequently, the recruitment of effector CD8+ T cells and Sin3B‐deficient PDAC cells form a positive feedback loop, amplifying the anti‐tumor effects and transforming the PDAC from a “cold” tumor to a “hot” tumor." (PMID 39316363, 2024). "As illustrated, tumor cell‐intrinsic Sin3B loss did not enhance the expression levels of Cxcl9 and Cxcl10 in either CAFs or macrophages within the TME." (PMID 39316363, 2024). "Taken together, SIN3B modulates tumor progression in a CD8+ T cell‐dependent manner." (PMID 39316363, 2024). "Given Sin3A and Sin3B share high sequence similarity, whether Sin3A has similar impact on the tumor microenvironment was evaluated." (PMID 39316363, 2024). "However, the role of SIN3B in tumor immunity hasn't been defined yet." (PMID 39316363, 2024). "Nevertheless, upon Kras activation, SIN3B enhances the expression of IL-1α, drives the production of SASP, and promotes the formation of pro-inflammatory tumor microenvironment." (PMID 37591827, 2023). "SIN3B plays a tumor-promoting role in a PDA mouse model, whereas SIN3B is up-regulated in ADM and PanIN." (PMID 37591827, 2023).
tumor (continued). "Using Ingenuity Pathway Analysis (IPA), the top networks that were altered from these gene lists were cell death/survival, cancer, and tumor morphology for SIN3A knockdown, and cancer, cell death/survival, and organismal injury and abnormalities for SIN3B knockdown." (PMID 27780928, 2016). "Of note, a study from Gabriel group conducted in vivo epigenetic CRISPR screens using mouse tumor models to systematically identify chromatin regulators influencing tumor immunity and the efficacy of ICB therapies, SIN3B emerged as one of the potential negative candidates of anti‐tumor immunity." (PMID 39316363, 2024). "However, as we found that SIN3B protein levels measured by IHC did not clearly correlate with GATA2 across a larger USC tumor cohort, it is likely that clinically relevant GATA2 regulation of SIN3B may not extend across the full USC tumor spectrum." (PMID 40168074, 2025).
cancer (5 papers, 2016 to 2025). A tumor composed of atypical neoplastic, often pleomorphic cells that invade other tissues. "SIN3B serves as a scaffold for chromatin-modifying complexes that have recently been implicated in the pathogenesis of cancers." (PMID 30935420, 2019). "Lowered expression levels of SIN3A and SIN3B have also been associated with the progression of many cancers." (PMID 27780928, 2016). "In pancreatic cancer, Sin3B was found to promote cancer progression by senescence-associated inflammation." (PMID 27780928, 2016). "It is important to point out that this is the first time that STAT2, NFE2L1, SIN3B and NOTCH2 genes are described associated to the cancer stroma." (PMID 31159827, 2019).
SIN3B also shares sentences with these, for which no sentence is quoted: alcoholics (1 paper); colon cancer (1); colon tumor (1); gastric cancer (1); invasive ductal carcinoma (1); lung carcinoma (1); melanoma (1).